MMP9 (matrix metallopeptidase 9)
Diseases named in the same sentence as MMP9 in open-access papers (continued):
Sharing a sentence is not in itself a finding about the gene and the disease.
cancer (continued). "Additionally, cross-talk between MMP-7 and MMP-9 leads to the cleavage of insulin-like growth factor-binding protein 2 (IGFBP-2), an angiogenic activator in major aggressive cancers via the transcriptional regulation of the VEGF gene, showing adverse effects in cancer angiogenesis in some tissues." (PMID 31921634, 2019). "Indeed, as the affinity of the N-TIMP2 and V3 domains of the heterodimer to their targets (MMP-9 and IL-17A, respectively) was not compromised, we attribute the improved ability of the heterodimer to inhibit cancer cell invasion to its ability to simultaneously bind both targets." (PMID 29983876, 2018). "ERα or MMP-9 may not act as key regulatory factors in cancer progression." (PMID 28915603, 2017). "The canonical proteolytic cascade that leads to enhanced cancer cell invasion is considered to be initiated by (pro)cathepsin B, which translocates from lysosomes to plasma membranes, where it may activate uPA, which in turn activates MMP-14, followed by activation of gelatinases MMP-2 and MMP-9." (PMID 28424417, 2017). "Therefore, the sustained promotion of cancer cell invasion by irradiated macrophages may be associated with the fact that MMP-2 and MMP-9 activity is not being affected by radiation exposure." (PMID 26735768, 2016). "Therefore, the suppression of phosphorylation of c-Met and the blockage of PI3K/Akt and NF-κB signaling pathways by the anticancer compounds could possibly inhibit the related downstream targets such as OPN, VEGF, MMP-9 and MMP-2, and thus suppress the cancer progression." (PMID 19796390, 2009). "Results of this analysis showed a significant increase in MMP2, MMP9, MMP12, and MMP16 levels in KIRC patients across different cancer stages, races, genders, and age groups when compared to normal controls." (PMID 38560573, 2024). "Although the expression of the MMP-9 and MMP-2 protein was elevated, it is likely that most cancer cells have not evolved to metastasis." (PMID 38955827, 2024). "With regard to TNF-α-induced and MMP-9-dependent fusion of M13SV1-EGFP-Neo breast epithelial cells and human MDA-MB-435 cancer cells, the potential role of β-catenin signaling is not yet clear." (PMID 36555709, 2022). "In the present study, changes in the expression of MMP2, MMP9, and MMP16 genes between patients with AML and people without cancer were examined." (PMID 34035811, 2021). "In line with this, Malaponte found a positive correlation between IL-6 and MMP-9 plasma concentrations in both DVT and non-DVT cancer patients." (PMID 32117207, 2019). "This review focuses on MMP-9, although it is not the only MMP member with vital roles in cancer development." (PMID 30262739, 2018). "If any effect of Apixaban exists on a cancer cell membrane "FXa-like" protease, this is not mediated by MMP2 and MMP9." (PMID 29023465, 2017). "These values were calculated for VEGF, IL-8 and MMP-9 between four groups i.e. (i) HD and COPD, (ii) HD and cancer, (iii) COPD and cancer and (iv) non-metastatic and metastatic." (PMID 27811960, 2016). "We found that rapamycin significantly inhibited MMP-2, but not MMP-9, compared with the control, suggesting that mTOR signaling plays significant roles both in maintaining NPC CSCs and in cancer progression." (PMID 26202311, 2015). "As a negative control, Catechin can also inhibit the growth of cancer cells, but has no inhibition effects on the migration and invasion of cancer cells, either the activity of MMP2 and MMP9." (PMID 26674531, 2015). "Compared to control group, higher plasma levels of CRP, fibrinogen, IL-6, TNF-α, IL-1β, MMP-9, VEGF, TF antigen, and sP-selectin were observed in cancer patients with and without DVT (P<0.01)." (PMID 26192925, 2015). "This is illustrated in gelatinase B/MMP-9 knockout mice, which do not resolve contact hypersensitivity reactions, implicating gelatinase B/MMP-9 in the down regulation of the immune response, suggesting an analogous role for gelatinase B/MMP-9 in cancer." (PMID 24473089, 2014).
cancer (continued). "Patients and controls did not have significant differences in their serum MMP-9 and TIMP-1 levels, although the ranges for MMP-9 and TIMP-1 concentrations were wider in cancer patients compared with healthy controls." (PMID 20671952, 2010). "Phenotypic resemblance of OGCs to the osteoclasts in the bone was confirmed with expression of MMP9, TRAP, and cathepsin K. The OGCs were negative for HLA-DR, and lacked antigen presentation abilities as anti-cancer defence." (PMID 20731838, 2010). "MMP-13 detected either in cancer cells or in adjacent fibroblasts, was not correlated with MMP-2 or MMP-9." (PMID 18373849, 2008). "Cancer cell spheroids disaggregated on extracellular matrices (ECM) and demonstrated enhanced expression of secreted pro-MMP2 as well as activated MMP2/MMP9 with no such activation of MMP's observed in monolayer cells." (PMID 17567918, 2007). "The results demonstrate that the storage of the urine samples at room temperature for >120 min significantly increased the levels of MMP9, APOE, ANG, and MMP10, which could change the final results (positive or negative to cancer)." (PMID 39857022, 2025). "We also observed the same trend for the mRNA of the mesenchymal marker hFN1, suggesting an increased aggressiveness of cells accompanied by an increase in MMP2 but not MMP9 mRNAs and of the CDH5 gene, fundamental to sustain cancer cell proliferation through vasculogenic mimicry." (PMID 40332096, 2025). "However, though there are many reports on the anticancer activities of A. vera, to our knowledge, there are no studies which correlate its anticancer activities with MMP-9 and MMP-2 enzymatic activity inhibition in cancer cells." (PMID 33308217, 2020). "In addition to stimulation of MMP-9 secretion in SAS cancer epithelial cells, ANE, but not arecoline, also stimulates MMP-9 mRNA expression of SAS cells and MMP-9 secretion of primary oral keratinocytes." (PMID 31831717, 2019). "Significantly, cancer cells on either 2-dimensional (2D) or 3D and non-malignant cells on 2D plastic do not produce NO and upregulate negative players: NFκB, EIF5A2, SCA1 and MMP-9 — that disrupt the network." (PMID 29560860, 2018). "Herein we demonstrated that ginsenoside Ro inhibited migration and invasion ability of cancer cells and their adhesion to human endothelial cells via its specific inhibition of expression of integrin αvβ6, MMP-2 and MMP-9 without producing any significant cytotoxicity to the tested cells." (PMID 28634392, 2017). "We examined the levels of MMP-2 and MMP-9, our data demonstrated that knockdown of HCRP-1 may promote cancer cell migration and invasion through increased expression of MMP-2 but not the MMP-9." (PMID 26304749, 2015). "After adding 740Y-P, PI3K agonist, the expression of SBEM protein in cancer cells of miR-186-5p mimic + 740Y-P group was significantly decreased than the miR-186-5p mimic NC + 740Y-P group, while the protein levels of p-PI3K, p-AKT, MMP1, MMP3 and MMP9 were not significantly changed." (PMID 37477531, 2023). "However, the JNK or JAK2 inhibitor could neither augment the anti-cancer effects of pKAL on STAT3 activity, nor on the expressions of CD44, Oct 3/4, β-catenin, and MMP-9 of RT-R-MDA-MB-231 cells." (PMID 32326231, 2020). "MMP9 expressed here by this aggressive oral tongue HSC-3 cell line may only be of minor importance, since its expression was not significantly increased in cancer cells after BMMSC interaction based on the microarray analysis." (PMID 24204919, 2013).
infection (354 papers, 2006 to 2026). The state of being infected such as from the introduction of a foreign agent such as serum, vaccine, antigenic substance or organism. "These markers showed strong associations with infection, while ferritin and MMP-9 were less informative." (PMID 41799724, 2026). "The results showed that pre-treatment with TAK-242 almost completely abrogated the MMP-9 expression caused by infection with S. Typhimurium." (PMID 38398037, 2024). "On the other hand, a high level of MMP9 causes damage to pulmonary tissue, and by increasing degradation of IL-8, it decreases neutrophils’ recruitment at the infection site." (PMID 35096290, 2021). "CRP associated with infection and injury in the organism had a significant effect on serum MMP9 levels." (PMID 34938784, 2021). "Mice deficient in MMP9 expression (MMP9−/− KO mice) were more resistant to infection, in comparison to WT mice, despite presenting equivalent viremia and similar levels of inflammatory cytokines and IFN-α in the circulation." (PMID 30984122, 2019). "Bronchial colonisation/infection with Treponema denticola and smoking are independently associated with elevated MMPs (MMP9/MMP12 and MMP8/MMP9, respectively) in the bronchial fluid." (PMID 26656474, 2015). "In summary, this cross sectional study has shown that smoking and bronchial colonisation/infection with Td are independently associated with elevated MMPs (aMMP8/MMP9 and MMP9/MMP12, respectively) in the bronchial fluid in a relatively large population." (PMID 26656474, 2015). "Recently, some studies have shown that significant increases in active MMP-9 are associated with a multiple organ dysfunction in an infection model." (PMID 24592193, 2014). "More recently, MMP-9 has been implicated in the regulation of monocyte recruitment in granuloma formation and bacterial growth in the M. marinum model of infection in zebrafish." (PMID 24136296, 2014). "Matrix metalloproteinase (MMP)-9 activity is closely associated with angiostrongyliasis meningitis caused by infection with A. cantonensis." (PMID 23505411, 2013). "In an attempt to characterize the mechanisms underlying A. cantonensis-induced blood-CSF barrier dysfunction, we investigated the association of NF-κB, MMP-9 and claudin-5 in the choroid plexus of the mouse brain after infection with A. cantonensis." (PMID 23505411, 2013). "Mouse models of genital tract infection have shown a reduced rate of scarring sequelae in MMP9 KO animals and that infection is associated with increased MMP9 in genital tract tissue (determined by zymography and gene expression)." (PMID 23457650, 2013). "Concerning matrix proteins, the real time QPCR assay confirmed that the pronephric expression of both mmp9 and mmp13 was up-regulated 5 days post infection with F. psychrophilum in resistant as well as in susceptible fish." (PMID 22720048, 2012). "Altogether, this confirms that during Hp infection the epithelial layer was eroded and damaged while curcumin was highly effective in suppressing MMP-9 and healing of overall damage caused by infection." (PMID 21283694, 2011). "However, clarithromycin has been observed to reduce the inflammation caused by infection and decrease vascular hyperpermeability by suppressing the induction of matrix metalloproteinases-9 (MMP-9) and monocyte chemoattractant protein-1 (MCP-1)." (PMID 39460768, 2024). "Therefore, high expression of MMP-9 is indicative of poor wound healing, which increases the risk of further infection, leading to prolonged inflammation, low levels of growth factors at the wound site, and further delay the wound healing." (PMID 36034877, 2022). "Moreover, MMP-9 associated IL-8 cleavage leads to a tenfold increase in neutrophil activation and recruitment to the infection site." (PMID 34066355, 2021). "Thus, MMP-9 has been intensively investigated for its role in membrane rupture and its association with in utero infection/inflammation." (PMID 33382822, 2020).
infection (continued). "As MMP-9 degrades type IV collagen, the main component of the basement membrane in the skin, and their activation causes excessive tissue damage by facilitating the migration of inflammatory cells to the infection site." (PMID 25393535, 2014). "MMP-9 could cause claudin-5 degradation and promote leukocyte infiltration into CSF via the paracellular route during infection with A. cantonensis in mouse choroid plexus." (PMID 23505411, 2013). "Furthermore, infection of MMP9-deficient mice showed that MMP9 was functionally required for neutrophil migration and control of viral replication in the respiratory tract." (PMID 22496659, 2012). "We observed decreased expression of several ECM components important for vascular integrity in the dura mater at day 7 post-infection including BM-associated collagens, laminins, and other structural proteins in addition to increased expression of matrix metalloprotease genes mmp3 and mmp9." (PMID 33524035, 2021). "To check whether expression profiles were correlated to enzyme activities and to exclude the possibility that infection caused alterations in the presence of MMP-9 and TACE only coincidentally, we performed a shedding assay for CD62L as an indicator for TACE-activity." (PMID 30897723, 2019). "Thus, MMP-9 could be an appropriate therapeutic target to stop severe tissue damage caused by infection or chronic inflammation." (PMID 25931987, 2015). "However, virtually no MMP9 secretion could be observed when the hematopoietic system was deficient in mmp9, suggesting that bone marrow-derived cells produced the majority of MMP9 in the lung after infection." (PMID 22496659, 2012). "In addition recent comparative studies of the role of MMP-9 in genital Chlamydia muridarum (MoPn) infection found greater MMP-9 transcription and activity during infection in those mouse strains exhibiting increased susceptibility to fibrotic sequelae following infection." (PMID 16643654, 2006). "Further research should include the correlation of MMP-9 with wound size, infection status, and healing trajectories in larger cohorts and aim to investigate MMP-9/TIMP-1 ratios as prognostic tools." (PMID 41189831, 2025). "MMP-9 levels also rose early, with a notable peak after 24 h in response to early reactivated Mtb, reflecting an infection-driven inflammatory response." (PMID 41450943, 2025). "At 4 h post-infection, explants infected with any of the three bacterial phases exhibited MMP-9 levels ranging from 204.6 to 255.4 pg/mL, representing an approximately 10-fold increase compared to uninfected controls." (PMID 41450943, 2025). "Due to the different types of infections, the number of leukocytes increases, which leads to an increased secretion of MMP-9." (PMID 41341833, 2025). "We also found MMP-9 enzymatic activity was higher in the patients with prodromal infection [512.8 (286.0–682.8) vs. 307.2 (203.2–487.0) ng/mL, P = 0.037]." (PMID 41341833, 2025). "This is especially relevant given that postoperative infection is often driven by early neutrophil recruitment and extracellular matrix remodeling, processes heavily influenced by matrix metalloproteinase-9 (MMP-9)." (PMID 41302087, 2025). "Across studies, signals also favored collagen‐based care for earlier area reduction and, in one trial, fewer infection‐related withdrawals; mechanistic work showed reductions in MMP‐9/TIMP‐2." (PMID 41249888, 2025). "In the present study, we found the circulating MMP-9 was significantly higher than that of the HCs, and positively correlated with prodromal infection in the patients with anti-GBM disease." (PMID 41341833, 2025). "Mtb induces the expression of matrix metalloproteinases (MMP-2, MMP-3, and MMP-9) in the placenta, with levels varying by bacterial metabolic state and time post-infection." (PMID 41450943, 2025).
infection (continued). "During acute injury or infection, transient MMP-9 release from neutrophils and macrophages facilitates leukocyte recruitment, pathogen clearance, and re-epithelialization, thereby accelerating tissue repair." (PMID 41304763, 2025). "In human decidual and placental models, P4 attenuates infection- or cytokine-driven pro-MMP-9 induction (e.g., E. coli stimulation of decidual cells) and reduces type IV collagen degradation in vitro, signifying a protective, remodeling-modulating role." (PMID 41304763, 2025). "The expression of the proinflammatory marker genes il1b and mmp9 is strongly induced in zebrafish larvae shortly after infection with M. marinum." (PMID 39336115, 2024). "The level of MMP-9 in the different groups was determined using the ELISA technique in the enteral (7dpi) and parenteral phase (54dpi) of infection." (PMID 39304848, 2024). "Matrix metalloproteinase MMP9 was also found to be upregulated in C. sinensis infection (P = 0.026), and this finding may be related to epithelial–mesenchymal transition, which was found above to be associated with this infection in our functional enrichment analysis of DEGs." (PMID 39652576, 2024). "To further explore the mechanisms behind PRV-induced blood-brain barrier permeability, we assessed the expression levels of MMP2, TIMP1, MMP9, and ZO-1 at various time points post-infection in bEnd.3 cells." (PMID 39436133, 2024). "Previous investigations have revealed that the infection-induced increase in MMP-9 induced by A. cantonensis is governed by the NF-kB or MAPK/ERK/AP-1 pathways." (PMID 38922036, 2024). "During infection, the level of the G-CSF in the bone marrow increases, and activates the synthesis of proteases, including matrix metalloproteinase 9 (MMP-9)." (PMID 38515741, 2024). "MMP-9 is crucial to the normal course of the immune response, facilitating leukocyte migration and invasion to the site of infection or inflammation." (PMID 38398037, 2024). "Our findings are consistent with studies of BCG-treated head and neck squamous carcinoma cells, which also showed reduced MMP-9 expression following infection with M. bovis BCG." (PMID 39684712, 2024). "The results indicated that the transcript levels of TNF-α, IL-8, and MMP-9 in the brain tissues of mice infected with ΔzmpC were significantly lower than those of the wild-type strain at 12 h post-infection." (PMID 39080654, 2024). "Our results clearly demonstrated a highly intracellular staining of MMP-9 in mononuclear cells infiltrating the lamina propria in the intestine and muscle tissues starting one week post infection in the infected-untreated group." (PMID 39304848, 2024). "As during infection, we found an increase in Mmp9+ cells (mean 46.0% Mmp9+ in the presence of HRASG12V versus 37.4% Mmp9+ in controls; n = 5; paired t test; P = 0.005)." (PMID 38413586, 2024). "For example, the lower upregulation of mmp9 and mmp13a during tamoxifen treatment is in line with a reduced inflammatory response in larvae with lower infection burden." (PMID 36475748, 2023). "Immunohistochemical staining was performed to detect the expression of matrix metalloproteinases (MMP2 and MMP9) in the brain; the expression was significantly increased from day 3 post-infection (P < 0.01)." (PMID 37452371, 2023). "MMP8 and MMP9 were upregulated in the mouse brain infected with CVS-B2c at 6 days post-infection which helped in enhancing blood-brain barrier (BBB) permeability." (PMID 37692167, 2023). "The skin and posterior-intestine of challenged fish responded quite similarly, with il-1β, il8 and mmp9 as the most highly induced genes, which provides evidence that an inflammatory response is activated upon infection with T. maritimum." (PMID 37731496, 2023). "The coinfection of salmon with Lactobacillus salmon and Lepeophtheirus salmonis showed that MMP9 was induced during the initial infection with Lactobacillus salmon." (PMID 36833402, 2023).